KIT (KIT proto-oncogene, receptor tyrosine kinase)
Diseases named in the same sentence as KIT in open-access papers (continued):
Sharing a sentence is not in itself a finding about the gene and the disease.
melanoma (continued). "Among the multiple genes affected by alterations that could potentially lead to melanoma development, mutations in c-KIT are becoming an appealing target for personalized therapy." (PMID 33233603, 2020). "However, they are typically found in four hot-spots (L576, K642, W557-V560, and D816-A829) where 70% of KIT mutations in melanoma can be found." (PMID 32344828, 2020). "Mutations of BRAF, NRAS, and KIT genes have been correlated to the development of melanoma." (PMID 31274706, 2020). "To determine the profile of patients who could benefit from KIT inhibitors, we investigated the mechanisms of resistance to KIT inhibition therapy by exploring the mechanisms associated with response to nilotinib in different KIT-mutated melanoma cell lines." (PMID 32344828, 2020). "Interestingly, a recent meta-analysis reported KIT mutations in 497 (9.5%) melanoma patients analyzing 5,224 patients from 32 studies selected." (PMID 32850962, 2020). "Other KIT inhibitors showed activity in KIT mutated advanced melanomas." (PMID 32850962, 2020). "Since more than half of the KIT mutant melanomas harbor exon 11 and exon 13 mutations, this is a significant patient population which could be treated with KIT inhibitors." (PMID 31848942, 2020). "Indeed, it has been found an increase of KIT mutations and/or CNVs in mucosal (39%), acral (36%), and melanomas arose on chronically sun-damaged skin (28%)." (PMID 32850962, 2020). "Data on the KIT mutation rate in melanoma in the central European region is missing." (PMID 31848942, 2020). "The most common c-KIT mutations in melanoma are L676P and K642E." (PMID 32054078, 2020). "In conclusion, to date it is recommended to test KIT mutations (especially exons 11 and 13) in acral, mucosal, and unknown origin melanomas, as well as cutaneous ones arising on chronically damaged skin, to offer an additional therapeutic option." (PMID 32850962, 2020). "For this reason, the aim of revising all studies evaluating the frequency of mutations of BRAF, NRAS, and KIT genes are to determine the correlation of the clinical-pathological characteristics of melanomas, and the demographic characteristics of the analysed populations." (PMID 31274706, 2020). "Activation of the MAPK pathway in KIT-mutated melanoma is seen in vivo in tumors, which exhibit activation of both MEK and ERK at baseline and upon treatment, suggesting that the MAPK pathway may be activated independently of KIT in these tumors." (PMID 32344828, 2020). "However, a recent meta-analysis of publications on KIT mutation frequencies in melanoma demonstrated that the average frequency is 9.5% with great variability." (PMID 31848942, 2020). "It should be highlighted that the NCCN guidelines describe that KIT inhibitors may be offered in patients with melanoma and activating KIT mutations." (PMID 32825562, 2020). "The CSD melanomas often have additional KIT, NRAS and NF1 mutations." (PMID 32283832, 2020). "KIT mutations rarely occur in posterior UM, and UM patients were not included in the phase II clinical trials studying the effect of the tyrosine kinase inhibitor imatinib in KIT-mutated melanoma." (PMID 32718045, 2020). "To resolve ITH in CSDhigh melanoma, we focused on one CSDhigh case with a KIT mutation." (PMID 31811783, 2020). "In this study BRAF, NRAS, KRAS, HRAS, PIK3CA and KIT mutations were examined in melanomas." (PMID 31277584, 2019). "Furthermore, phase 2 clinical trials with dasatinib and saracatinib had minimal clinical activity as a single agent in patients with advanced melanoma, and response rate to dasatinib among melanoma patients with KIT activating mutation was low." (PMID 31040916, 2019). "However, a resection specimen take from right vulva 39 months later showed malignant melanoma harboring a KIT p.N655K mutation at 3.7% VAF in a context of 30–50% estimated tumor cellularity." (PMID 31277584, 2019).
melanoma (continued). "Furthermore, somatic mutations in KIT have been reported in 15–20% of mucosal melanomas, and are more commonly observed in anorectal and vulval/vaginal tumors (15–25%)." (PMID 30847022, 2019). "The receptor tyrosine kinase (RTK) c-KIT is recurrently mutated in a small percentage of melanomas." (PMID 30987166, 2019). "Permanently active KIT mutations are found in about 25% of mucosal melanomas and seminomas." (PMID 31484543, 2019). "However, in contrast to dasatinib, GSK414 unequivocally caused the downregulation of KIT in the melanoma cells." (PMID 30931942, 2019). "KIT mutation is most frequently observed in acral, mucosal and chronically sun-exposed melanomas." (PMID 30181807, 2018). "Interestingly, clinical response to Imatinib was limited to mucosal melanomas with KIT mutations, while tumors with amplification of wild-type KIT had no response." (PMID 29385676, 2018). "The presence of KIT mutations in malignant melanomas has already been demonstrated in the literature, in particular in melanomas of the mucosa (21% of KIT mutations), acral melanomas (11% of KIT mutations), and skin melanomas caused by chronic exposure to sunlight (17% of KIT mutations)." (PMID 29796159, 2018). "Given the evidence of a possible pathogenic role of the KIT gene in a number of mucosal melanomas, including those of the head and neck, screening for KIT aberrations may have diagnostic value, and the gene may represent a therapeutic target in these patients." (PMID 29796159, 2018). "This combination merits further investigation in patients with KIT-mutated melanoma." (PMID 28428884, 2017). "Similarly, c-KIT protein expression has been reported in up to 90% of mucosal melanoma tumors and roughly 20% harbor KIT mutations." (PMID 28428884, 2017). "Notably, this patient had a point mutation in exon 11 at L576P, the most common KIT mutation in melanoma." (PMID 28428884, 2017). "On the one hand, melanomas with chronic sun-induced damage (CSD) harbor mutations in KIT proto-oncogene receptor tyrosine kinase (KIT, Gene ID: 3815), NF1, NRAS, and BRAF but typically not BRAF(V600E), the specific BRAF mutation that commonly arises in atypical melanocytic neoplasms." (PMID 28265786, 2017). "The melanoma responder was KIT mutated and the GIST responder was wild-type." (PMID 28428884, 2017). "The results of an ongoing expansion cohort targeting this population will provide additional evidence as to whether to pursue this combination in KIT-mutated melanoma." (PMID 28428884, 2017). "KIT is a gene which is found mutated in approximately 3% of melanomas." (PMID 28484715, 2017). "Patients with melanomas harboring KIT mutations are eligible for imatinib therapy." (PMID 28484715, 2017). "Three KIT mutations were identified, and correlated with known KIT mutations by pyrosequencing performed at University Hospital Birmingham in 2 cases, which was from a skin primary and melanoma from an unknown primary site." (PMID 28228113, 2017). "Mutations in the BRAF and KIT genes in subsets of melanoma have been reported." (PMID 27124046, 2016). "Both V559A and K642E mutations of KIT were also identified as somatic mutations in melanoma." (PMID 27777718, 2016). "The mutational status for BRAF, NRAS and c-KIT was assessed in the melanoma samples." (PMID 26909610, 2016). "Likewise, KIT L576P, the most common KIT mutation in melanoma, has been shown to induce structural changes in KIT that reduce the affinity for imatinib but not for dasatinib." (PMID 27095580, 2016). "In contrast, BRAF mutations are rarely found in uveal melanomas or melanomas arising from the mucosa or internal organs, and mutations in the receptor tyrosine kinase KIT are found more frequently in lentigo maligna melanoma, acral melanoma and melanomas arising from the mucosa or internal organs." (PMID 27057633, 2016). "KIT mutations detected in tDNA of 4 melanomas were also observed in the cfDNA DST panel." (PMID 26452027, 2015).
melanoma (continued). "Regarding the other oncogenic mutations that have been described in either cutaneous or mucosal melanomas, c-KIT missense mutations and/or copy number amplifications occur in about 21% of mucosal melanomas, while they are absent in non-sun-damaged cutaneous melanomas." (PMID 25695059, 2015). "For instance, KIT mutations are more common in acral than in the other melanomas." (PMID 26106605, 2015). "Mucosal melanomas have an increased prevalence of c-KIT mutations, seen in about 20-25 % cases." (PMID 26334521, 2015). "We previously suggested that imatinib can be effective when melanoma tumors harbor KIT mutations." (PMID 25609545, 2014). "In contrast, melanoma patients have a higher prevalence of KIT mutations in exon 11 near the C-terminus as well as KIT mutations in exon 13 and exon 17, which may confer resistance to imatinib therapy." (PMID 25609545, 2014). "Together, our data suggest that malignant transformation in melanomas may be associated with loss of KIT and expression of EPO-R and ErbB4." (PMID 24489649, 2014). "V560G/D mutations represent the majority of KIT mutations found in GISTs and melanoma." (PMID 25079768, 2014). "In the current study we analyzed frequency and type of oncogenic mutations in known oncogenes (BRAF, NRAS, and KIT) involved in melanoma development in large contemporary series of MUP patients with long follow-up, and we correlated these outputs with disease clinical features and outcome." (PMID 24866436, 2014). "A recent phase II trial of imatinib in selected patient population with mucosal, acral, or chronically sun-damaged melanoma concluded with an overall disease-control rate of 50%, but the responses were observed in 77% of patients with mutated KIT and only in 18% of those with amplified KIT." (PMID 24743024, 2014). "KIT mutations have been found in the rare subgroup of patients with mucosal melanoma, acral melanoma and melanoma arising on chronically sun damaged skin, which has raised the possibility of utilizing imatinib mesylate for targeted therapy in these types of melanoma." (PMID 25609545, 2014). "While mucosal and acral melanomas account for ~65% of all melanomas in Chinese and other Asian populations, in Caucasian populations the predominant location is the trunk and legs, with detection of KIT mutations identified in ≤11% of all melanomas in China." (PMID 25120707, 2014). "Since SCF is normally produced by keratinocytes and other dermal cells, loss of expression of c-KIT may allow malignant melanoma cells to escape c-KIT/SCF mediated apoptosis, contributing to growth and tumor metastasis." (PMID 22839358, 2012). "A number of tumour types are associated with activation of c-KIT through its overexpression or through activating mutations, while in highly metastatic melanomas, breast cancer and thyroid carcinoma the progression into a malignant phenotype correlates mostly with loss of c-KIT expression." (PMID 22233760, 2012). "Promising biomarkers for melanoma include KIT and BRAF gene mutations." (PMID 22123319, 2011). "KIT mutations were found in 38% of mucosal and in 6% of acral melanomas." (PMID 20372153, 2010). "Similarly, in melanoma, there are early reports of success when selected groups of patients harbouring activating mutations in the receptor tyrosine kinase c-KIT have been treated with imatinib." (PMID 19156138, 2009). "We could show KIT mutations in 2 out of 12 mucosal melanomas from head/neck, 3 out of 11 from the genitourinary tract and 1 out of 8 from the anal/rectal tract." (PMID 19018266, 2008). "The identification of the KIT mutation as a poor prognostic factor in high-risk stage II melanomas suggests that testing for this mutation may provide an opportunity for the adjuvant use of KIT inhibitors to treat these otherwise treatment-resistant triple wild-type tumors." (PMID 38158497, 2024). "Notably, the D816V KIT mutation has rarely been reported in melanoma." (PMID 37372988, 2023).
melanoma (continued). "However, whether the novel mutations in exon 13 of the c-KIT gene were responsible for imatinib intolerance in the GIST or melanoma patients remains elusive." (PMID 35720122, 2022). "However, the responses of Sunitinib in patients with non-KIT-mutated indicated Sunitinib might have other targets associated with melanoma growth." (PMID 36588679, 2022). "Furthermore, a phase II clinical trial of nilotinib in 25 patients with unresectable melanoma with KIT mutations demonstrated a response rate of 20% and a disease control rate of 56% in patients with exon 11 or 13 mutations after receiving 400 mg oral nilotinib twice daily for 6 months." (PMID 35954441, 2022). "Thus, activating c-KIT mutations act as the target of clinical therapies in melanoma." (PMID 35720122, 2022). "Additionally, the high frequency of KIT mutations in Asians may contribute to the low response rates of Asians with mucosal melanoma undergoing treatment with targeted therapies." (PMID 34149718, 2021). "Also, KIT mutations have previously been found to determine a worse melanoma survival." (PMID 33648909, 2021). "Furthermore, the KIT mutation has the highest rate among all mutations in mucosal melanoma types." (PMID 34065883, 2021). "Accordingly, it was predicted that imatinib could be a promising candidate to synergistically enhance antitumor T-cell activation provided by CTLA-4 blockade immunotherapy but showed response in one KIT-mutated melanoma patient and further investigation are still ongoing." (PMID 33918490, 2021). "KIT, which is a famous oncogene, is often mutated in advanced melanoma and contributes to malignancy progression and an unfavorable prognosis, while highly expressed TNFSF14 in human melanoma cells and microvesicles may contribute to the mediation of T cell responses to cancer cells." (PMID 32411243, 2020). "However, it has to be considered that the BRAF/NRAS mutation frequency is very low in mucosal melanoma, therefore the KIT mutation rate must be much higher in mucosal melanoma as compared to cutaneous locations but a statistical analysis cannot be done on our small cohort." (PMID 31848942, 2020). "Finally, dasatinib was evaluated in 22 patients with advanced or metastatic KIT mutated melanoma." (PMID 32850962, 2020). "Therefore, particularly in mucosal melanomas, a correlation between p-Akt1 overexpression and c-KIT mutation may help to understand how these pathways are important for melanoma pathogenesis and patient outcomes." (PMID 30647870, 2018). "In addition we addressed the issue of whether the lentiginous growth pattern and extended field effect observed in melanomas with somatic mutations in KIT were a direct consequence of KIT pathway activation." (PMID 27322141, 2016). "Patients with melanomas containing activating mutations in KIT have been reported to respond to imatinib therapy; however, it remains uncertain whether mutations considered to be predictive of imatinib resistance can respond to second-generation KIT kinase inhibitors." (PMID 20372153, 2010). "Therefore, therapeutic c-KIT blockade could be considered for the treatment of patients with mucosal melanomas and an activating KIT mutation." (PMID 19018266, 2008). "They analyzed the enriched gene of NRAS‐mutant melanoma cell lines, and the results showed that the overexpression of Axl, c‐KIT, and c‐MET, which as the target for amuvatinib." (PMID 41492362, 2026). "Here, we report that the mTOR inhibitor sapanisertib improves the efficacy of combined belvarafenib and cobimetinib therapy in NRAS, NF1, and KIT-mutant melanomas." (PMID 42091854, 2026). "This study increases our understanding of biomarkers NRAS and KIT and provides a foundation for optimizing melanoma care, contributing to advancements in precision oncology." (PMID 41378737, 2026). "Mucosal and acral melanoma are the melanoma types with the highest prevalence of KIT alterations, around 20–30% and 10–15%, respectively." (PMID 39859576, 2025).
melanoma (continued). "While initially used in chronic myeloid leukemia, it has also been evaluated in KIT-driven melanomas, particularly acral and mucosal subtypes." (PMID 41301010, 2025). "Future work should aim to better define the immunogenicity of KIT-driven melanomas and clarify the optimal sequencing or combination of ICIs and TKIs to achieve durable clinical benefit." (PMID 41301010, 2025). "In a retrospective study from MD Anderson, 55 patients with advanced KIT-mutant melanoma were treated with anti-CTLA-4 and/or anti-PD-1 therapy." (PMID 41301010, 2025). "The MAPK pathway has a crucial role in melanoma pathogenesis and is activated by mutations in the key signalling pathway members, including BRAF, NRAS, NF1 and KIT." (PMID 41017066, 2025). "This case suggests the possibility of undetected KIT alterations or alternative mechanisms of nilotinib sensitivity in mucosal melanoma." (PMID 41301010, 2025). "RT-qPCR assay proved that Artemisinin significantly decreased KIT expression in B16 melanoma cell line." (PMID 39744440, 2025). "Clinical trials have shown ORRs in the range of 16–30% and disease control in 30–70% of KIT-mutant melanoma patients on TKIs, especially those with classic activating mutations." (PMID 41301010, 2025). "In contract, the adoption of ddPCR for detecting common melanoma mutations including BRAF, NRAS, KIT, and TERT significantly improved sensitivity, allowing ctDNA to be distinguished from total cfDNA in approximately 80% of melanoma patients." (PMID 39859576, 2025). "Approximately 85% of melanomas harbor primary pathogenic alterations in key genes such as BRAF, NRAS, NF1 or KIT, which include mutations, deletions or amplifications." (PMID 39859576, 2025). "A recent development for melanoma with c-KIT gene alterations is the combination of KIT inhibitors and PD-1 inhibitors (NCT05274438)." (PMID 40429850, 2025). "A number of KIT inhibitors have been developed and are in clinical trials to target unresectable melanomas, including imatinib, nilotinib, dasatinib, and sunitinib." (PMID 39858514, 2025). "Immune checkpoint inhibitors, the standard treatment for melanoma therapy, remain indicated for KIT-mutant cases and have demonstrated efficacy in some patients, particularly in the metastatic setting and in TKI-resistant mutations." (PMID 41301010, 2025). "Mutations of the BRAF gene are the most frequent, detected in approximately 38.5% of melanomas, while NRAS mutations occur in about 16.4% and KIT mutations in around 10% of cases." (PMID 41007741, 2025). "Similar to findings in White melanoma studies, variants in BRAF (25%), NRAS (20%), NF1 (17%), and KIT (17%) were prevalent in Japanese melanomas (Appendix Fig A1B)." (PMID 39823560, 2025). "We applied Artemisinin to melanoma both in vitro and in vivo, and then a western blot assay was performed to confirm c-KIT as a target of Artemisinin." (PMID 39744440, 2025). "Artemisinin blocked melanoma growth, migration, and invasion by inhibiting the c-KIT/PI3K/AKT signaling pathway." (PMID 39744440, 2025). "A dedicated clinical study evaluating the efficacy of avapritinib in patients with KIT-mutant melanoma and CNS metastases would be instrumental in defining its therapeutic role in this setting." (PMID 41301010, 2025). "Artemisinin exerts its anti-melanoma effect through the c-KIT/PI3K/AKT pathway both in vivo and in vitro, which supports their potential therapeutic effect for post-surgery treatment of cancer patients." (PMID 39744440, 2025). "Clinical studies specifically evaluating KIT-mutant acral, mucosal, uveal, and sun-damaged melanomas have reported heterogeneous yet encouraging results." (PMID 41302945, 2025). "Given the rarity of KIT-driven melanoma and its distinct molecular features—including a lower tumor mutational burden and non-UV-driven pathogenesis—the efficacy of ICIs in this subset remains less well characterized." (PMID 41301010, 2025).